CCL22 (C-C motif chemokine ligand 22)
Diseases named in the same sentence as CCL22 in open-access papers (continued):
Sharing a sentence is not in itself a finding about the gene and the disease.
prostate carcinoma (6 papers, 2017 to 2023). A carcinoma that arises from epithelial cells of the prostate gland. "Next, the effects of CCL17 and CCL22 on prostate cancer cells were analyzed using a transwell migration assay and a wound-healing assay." (PMID 28039457, 2017). "Moreover, AZD5363, a potent inhibitor of Akt, inhibited CCL17- and CCL22-induced prostate cancer migration." (PMID 28039457, 2017). "In summary, CCL2 and CCL22 secretion in the prostate cancer tumor microenvironment may induce not only direct metastasis of prostate cancer cells, but also promote the activation of TAMs and Tregs, which facilitate a suitable environment for cancer progression." (PMID 30871130, 2019). "We searched for mRNA expression of CCL17, CCL22, CCR4, and Foxp3 in the publicly available transcriptomic dataset of human prostate cancer from TCGA PanCancer Atlas (n=493)." (PMID 35131860, 2022). "High mRNA expression of CCL17, CCL22, CCR4, and Foxp3 was detected in 5.0%, 3.0%, 2.2%, and 5.0% of patients with prostate cancer, respectively." (PMID 35131860, 2022). "CCR2 and CCR4 antagonists clearly inhibited the migration ability of prostate cancer cells, which was induced by CCL2 and CCL17/CCL22." (PMID 28039457, 2017). "CCL22 and CCL17 were M2-type macrophage markers, and U937-M cells took on the characteristics of M2-type macrophages after co-culture with prostate cancer cells." (PMID 28039457, 2017). "The migration and invasion of prostate cancer cells via enhanced phosphorylation of Akt were promoted by CCL17 and CCL22." (PMID 28039457, 2017). "Notably, addition of CCL2 induced both CCL22 and CCR4 expression in prostate cancer cells; CCL22 subsequently promoted the migration and invasion of prostate cancer cells in an autocrine manner, via enhanced phosphorylation of Akt." (PMID 30871130, 2019). "The addition of CCL2 induced CCL22 and CCR4 production in prostate cancer cells." (PMID 28039457, 2017). "Additionally, when CXCR2 expression is increased in prostate cancer cells, the expression of secretory factors such as VEGF, angiogenin, thrombopoietin, oncostatin M, IGF-1, CCL2/MCP-1, CCL22/MDC, and M-CSF is increased, namely factors that are involved in tumorigenesis." (PMID 37108425, 2023).
viral infection (6 papers, 2010 to 2025). "By reviewing the literatures, we found that the upregulation of CCL22 played an important role in bacterial and viral infection-associated tumors." (PMID 35295948, 2022). "Markers of the intensity of the viral infection (CXCL10, CCL22) were associated with response, suggesting that the downstream effects of viral replication contributed to antitumor immunity and potentiated the activity of pembrolizumab." (PMID 36445410, 2023). "Within the infectious group, MDC/CCL22 levels were significantly higher in non-viral infections compared to viral infections (p = 0.0048) and controls (p = 0.0012)." (PMID 30379898, 2018). "MDC/CCL22, the cytokine we identify as potentially useful in distinguishing viral from non-viral infection, is involved in chronic inflammation, lymphocyte and dendritic cell homing, and in the overall modulation of innate immunity during infections." (PMID 30379898, 2018).
lung adenocarcinoma (5 papers, 2020 to 2025). A carcinoma that arises from the lung and is characterized by the presence of malignant glandular epithelial cells. "Lung adenocarcinoma cell lines with EGFR mutations are also known to recruit regulatory T cells (Tregs) as a result of high C-C motif chemokine 22 (CCL22) expression, creating a suppressive tumor-immune microenvironment." (PMID 36672698, 2023). "After Bonferroni correction, only CXCL13 and CCL22 were found to be independently related to the risk of early-stage lung adenocarcinoma." (PMID 32714866, 2020). "CCL22/MDC expression is not changed by chronic hypoxia as shown by studies on hepatocellular carcinoma cells and lung adenocarcinoma." (PMID 32781743, 2020).
oral cancer (5 papers, 2019 to 2022). "CCL22 is implicated in the recruitment of T regulatory cells, and its expression in oral cancer patients has been associated with a reduced disease-free survival." (PMID 35048046, 2021). "CCL22 expression in oral cancer cells was induced by IL-1β secreted by cancer-associated fibroblasts, suggesting a new therapeutic prospect by targeting the IL-1β-CCL22-CCR4 signaling axis for the treatment of oral cancer." (PMID 34177907, 2021). "Cancer-associated fibroblast-secreted IL-1β may activate CCL22 signaling in oral cancer." (PMID 35860473, 2022). "A recent report demonstrated that IL-1β produced by CAFs induces CCL22 mRNA overexpression in oral cancer cells." (PMID 35048046, 2021). "CCL22, as an oncogene, is upregulated in oral cancer specimens to promote the migration and infiltration of Treg cells." (PMID 34177907, 2021). "Increased CCL22 mRNA levels are correlated with increased FoxP3 mRNA levels in oral cancer specimens." (PMID 31842422, 2019). "For example, CAF-derived IL-1β can induce C motif chemokine ligand 22 (CCL22) mRNA expression in oral cancer cell lines through the activation of transcription factor nuclear factor kappa B (NF-κB), which is associated with cell transformation and regulatory T cell infiltration." (PMID 32957712, 2020).
breast tumor (4 papers, 2013 to 2023). "CCR4 is known to be down regulated on Tregs after their sensitization to CCL22 but other chemokine receptors, such as CCR6, which are expressed on these Tregs, which is interaction with CCL20 production by breast tumor cells." (PMID 24124553, 2013). "Furthermore, based on the homing activity of Tregs to cancer, such as from the CCL22/CCR4 axis, SRC-3 KO Tregs can aggressively move into breast tumors." (PMID 37253006, 2023). "Similarly, Gobert and colleagues found a strong correlation between infiltrating Foxp3+ Treg cells and CCL22, but not with CCL17, in breast tumor." (PMID 26020249, 2015).
eosinophilic pneumonia (4 papers, 2019 to 2025). An inflammatory lung disorder characterized by an increased number of eosinophils in the lungs. "When we analyzed other studies on this topic, we noted that, in lung pathologies of other origins (i.e., eosinophilic pneumonia and pulmonary hemorrhage), CCL22/MDC concentrations were significantly higher than in healthy donors." (PMID 36012323, 2022). "CCL22 (MDC) participates in macrophage recruitment and plays a pivotal role in several Th2 conditions such as asthma and eosinophilic pneumonia." (PMID 36836922, 2023).
head and neck cancer (4 papers, 2019 to 2024). A primary or metastatic malignant neoplasm affecting the head and neck. "Prognostic analysis of data from The Human Protein Atlas showed that CCL22 expression in tumors was favorably associated with survival in colorectal, endometrial cancers, and in head and neck cancers." (PMID 33202734, 2020). "Silencing CCL22 expression could reduce cell migration and invasion in head and neck cancer." (PMID 39513112, 2024). "High expression levels of CCL22 and CCL17 are positively correlated with CD4+ T cell infiltration and a favorable prognosis with ICI treatment in patients with head and neck carcinoma." (PMID 38026978, 2023).
head and neck squamous cell carcinoma (4 papers, 2015 to 2025). A squamous cell carcinoma that arises from any of the following anatomic sites: lip and oral cavity, nasal cavity, paranasal sinuses, pharynx, larynx, and salivary glands. "Additionally, a positive correlation between Treg concentration in the TME and serum IL-10 levels, as well as the extent of CCL22-positive cell infiltration, has been documented in patients with head and neck squamous cell carcinoma (HNSCC) and ESCC." (PMID 40134607, 2025). "Studies on head and neck squamous cell carcinoma (HNSCC) have identified CCL22 and CCL17 as important prognostic factors for patient survival and response to immune checkpoint blockade therapy." (PMID 38791448, 2024). "In accordance with Schott’s findings for patients with head and neck squamous cell carcinoma (HNSCC), we also found significantly elevated level of the CCR4 ligand, CCL22, in SSCC patients compared to healthy subjects." (PMID 26020249, 2015). "CCR4+ head and neck squamous cell carcinoma (HNSCC), compared to CCR4-, promotes lymph node metastasis with TAM-derived CCL22." (PMID 39199574, 2024).
influenza (4 papers, 2014 to 2025). An acute viral infection of the respiratory tract, occurring in isolated cases, in epidemics, or in pandemics; it is caused by serologically different strains of viruses (influenzaviruses) designated A, B, and C, has a 3-day incubation period, and usually lasts for 3 to 10 days. "Although in influenza-infected mice, expression of CCL17 and CCL22 by airway epithelial cells is associated with imprinting of CCR4+CD4+ T cells by lung dendritic cells, our findings suggest that this does not occur with human RSV." (PMID 31815739, 2020). "Notably, transcriptional studies in lung tissues of Estriol treated mice post influenza A infection revealed a correlation between upregulation of CCL19 and CCL22 genes with reduced lung inflammation and pathology due to influenza." (PMID 36119026, 2022). "This suggests that high levels of CCL22 pre-vaccination, possibly as part of a negative feedback loop, may be associated with increased systemic inflammation, which has been previously associated with serological response to influenza vaccination." (PMID 40881708, 2025).
ischemic heart disease (4 papers, 2018 to 2024). "A separate study in humans from the same group found increased CCL22 abundance associated with ischemic heart disease progression." (PMID 31393916, 2019). "A comparative study to evaluate the CXCL10, CCL20 and CCL22 levels in patients with ischemic heart disease." (PMID 30210493, 2018).
leukemia (4 papers, 2021 to 2024). A malignant (clonal) hematologic disorder, involving hematopoietic stem cells and characterized by the presence of primitive or atypical myeloid or lymphoid cells in the bone marrow and the blood. "It has been shown that Tregs strongly express CCR4, a chemokine receptor for CCL17 or CCL22, on their surface as compared to effector T cells in leukemia studies." (PMID 33816236, 2021). "Additionally, it has been demonstrated that primary leukemia cells secrete CCL22 and CCL17 in response to CD40 ligation, indicating that the chemokines may direct B-cell responses that are dependent on T lymphocytes in secondary lymphoid tissues by enlisting helper T lymphocytes and dendritic cells." (PMID 37259456, 2023). "Ex vivo experiments from different research groups indicate that leukemia stimulation of primary BM-MSCs is able to specifically upregulate the expression of CCL2, CXCL10, CCL22, CXCL8, and CXCL1." (PMID 33922612, 2021). "Interestingly, these chemokines, abundant in leukemia-conditioned MSC supernatants, were able to potently attract B-ALL cells that, besides CXCR4, showed high membrane levels of CCR4 (CCL22 and CCL2 receptor) and variable levels of CXCR1/2 (CXCL1 and CXCL8 receptors)." (PMID 33922612, 2021).
lymph node metastasis (4 papers, 2019 to 2022). "The IHC data showed that CCL22-positive TAMs were primarily distributed in regions surrounding tumor cells and were most positively associated with lymph node metastasis among the various clinical parameters." (PMID 35962191, 2022). "The higher number of CCL22+ cells was significantly associated with lymph node metastasis (p < 0.05), FIGO stages (p < 0.05), therapeutic strategies (p < 0.05), and survival status (p < 0.05)." (PMID 31842422, 2019). "The higher number of infiltrating CCL22+ cells (CCL22high) group was associated with lymph node metastasis (p = 0.004), Fédération Internationale de Gynécologie et d’Obstétrique (FIGO) stages (p = 0.010), therapeutic strategies (p = 0.007), and survival status (p = 0.002)." (PMID 31842422, 2019). "CCR2, CCR4, and their respective ligand-mediated pathways, CCR2\CCL2 axis and CCR4\CCL22 axis, are considered to be important mechanisms of lymph node metastasis." (PMID 31672162, 2019). "The group with lower number of CCL22 (+) cells had 42.7% (88/206) lymph node metastasis, 55.8% (115/206) FIGO stage I to II, 38.3% (79/206) cases treated by surgery, and 11.2% (23/206) in death." (PMID 31842422, 2019). "The group with the higher number (n > 11) of CCL22 (+) cells had 12.5% (3/24) of cancer with lymph node metastasis, 83.3% (20/24) FIGO stage I to II, 70.8% (17/24) cases treated by surgery, and 37.5% (9/24) of cancer with death." (PMID 31842422, 2019).
Miscarriage (4 papers, 2018 to 2024). A pregnancy that ends at a stage in which the fetus is incapable of surviving on its own, defined as the spontaneous loss of a fetus before the 22th week of pregnancy. "Given that Treg infiltration into the decidua has been associated with adverse pregnancy outcomes including miscarriage, CCL22 induction may directly impact maternal-fetal tolerance in the context of congenital infection." (PMID 35975985, 2022). "The precise role of CCL22 in human pregnancy is unknown, but maternal cells express CCL22 at low levels throughout pregnancy, with increased levels associated with miscarriage." (PMID 29317509, 2018). "Of note, we found that CCL22, a chemokine known to be expressed constitutively during pregnancy and that has also been found to increase during miscarriage, was induced by >400-fold in infected PHT cells based on RNA-seq and confirmatory RT-qPCR." (PMID 29317509, 2018).
Pruritus (4 papers, 2016 to 2023). Pruritus is an itch or a sensation that makes a person want to scratch. "Among the studied chemokines (C-C Motif Chemokine Ligand (CCL) 2/MCP-1, CCL3/MIP-1α, CCL4/MIP-1β, CCL5/RANTES, CXCL8/IL-8, CCL17/TARC, CCL18/PARC, CCL22/MDC), only CCL17/TARC showed a positive correlation with pruritus intensity." (PMID 37834183, 2023). "The aim of the study was to analyse serum concentrations of CCL2/MCP-1, CCL3/MIP-1α, CCL4/MIP-1β, CCL5/RANTES, CCL17/TARC, CCL18/PARC, CCL22/MDC and CXCL8/IL-8, and their correlation with PsO severity and pruritus intensity." (PMID 36362116, 2022).
renal cell carcinoma (4 papers, 2021 to 2023). "Reported that miR-34a-5p/CCL22 axis positively regulates the proliferation and metastasis of renal cell carcinoma (RCC)." (PMID 37021054, 2023). "C–C motif chemokine 22 (CCL22), a chemokine that acts on CCR4 + cells such as dendritic and T cells, participated in the progression of renal cell carcinoma and showed a connection with circ_0039569 and miR-34a-5p." (PMID 35831825, 2022). "CCL22, CRP, ICAM1, IFNG, PDGFRA, TGFB1 and TNFSF11 have been confirmed to be involved in the malignant progression and metastasis of renal cell carcinoma through different biological mechanisms." (PMID 34187413, 2021).
type 1 diabetes (4 papers, 2017 to 2025). "The simultaneous upregulation of chemokines that promote (CXCL10, CXCL9) and protect against (CCL17, CCL22) type 1 diabetes suggests a complex immune response to PET microplastics." (PMID 40597598, 2025). "In contrast, CCL22-mediated recruitment of Treg cells to the pancreas protects against autoimmune diabetes in a murine type 1 diabetes model." (PMID 30467506, 2018).
Arthritis (3 papers, 2018 to 2023). Inflammation of a joint. "Other resolutive chemokines (RANTES/CCL5, MIP2/CXCL2, MDC/CCL22), and cytokines IL-1RA and IL-10 were quantified in SuperMApo and thus added to recombinant TGF-β (all in similar quantity than measured in SuperMApo) to treat arthritis." (PMID 30542342, 2018).
autism (3 papers, 2013 to 2020). Persistent deficits in social interaction and communication and interaction as well as a markedly restricted repertoire of activity and interest as well as repetitive patterns of behavior. "Similar genetic studies of MDC/CCL22 gene are recommended in children with autism." (PMID 23782855, 2013).
chronic obstructive pulmonary disease (3 papers, 2020 to 2024). A chronic and progressive lung disorder characterized by the loss of elasticity of the bronchial tree and the air sacs, destruction of the air sacs wall, thickening of the bronchial wall, and mucous accumulation in the bronchial tree. "For example, miR-34c-5p targets C-C motif chemokine ligand 22 (CCL22) to alleviate the development of chronic obstructive pulmonary disease." (PMID 38374244, 2024).
colitis (3 papers, 2020 to 2025). Inflammation of the colon. "Several genes such as Gata3, Itk, Ccl8, Ccl22, Ccr4, Crlf2, Il9r, Il1rl1, and Arg2 are regulated concordantly in T-cell transfer colitis, acute DSS colitis and the time point representing high inflammation in the DSS time course." (PMID 34136502, 2021).
endometrial cancer (3 papers, 2020 to 2024). Primary or metastatic malignant neoplasm involving the endometrium (mucous membrane that lines the endometrial cavity). "Our study aims to identify the expressing cell types and to evaluate the prognostic significance of CCL22 secretion and its association with Treg invasion in endometrial cancer (EC), an immunogenic cancer." (PMID 39232378, 2024). "•The impact of the chemokine CCL22 on the outcome of endometrial cancer (EC) patients depends on its localization and producing cell type." (PMID 39232378, 2024).
endometriosis (3 papers, 2024 to 2025). The growth of functional endometrial tissue in anatomic sites outside the uterine body. "Recent studies on immune protein analysis have demonstrated that the expression levels of TNFα, MDC (monocyte chemoattractant protein, also referred to as CCL22), and IL-1α are elevated in patients suffering from endometriosis-related chronic pain." (PMID 40004233, 2025). "Besides EC, there are only a few publications on CCL22 and endometriosis and healthy endometrium, which describe an increased CCL22 level in combination with progesterone treatment." (PMID 39232378, 2024).
experimental autoimmune encephalomyelitis (3 papers, 2015 to 2021). An autoimmune demyelinating disease of the central nervous system that is produced experimentally in animals by the injection of homogenized brain or spinal cord in Freund's adjuvant. "The importance of CCR4 and its two ligands, TARC (CCL17) and CCL22, has also been noticed in central nervous system autoimmunity and studied in the experimental autoimmune encephalomyelitis murine model." (PMID 34539561, 2021). "The evidence is consistent for the involvement of CCL17, CCL22 and CCR4 in the experimental autoimmune encephalomyelitis model of MS72–74." (PMID 32179746, 2020).
inflammatory skin disease (3 papers, 2015 to 2023). Inflammatory skin disorders covers a broad category that includes many conditions ranging in severity, from mild itching to grave medical health complications These disorders are common in people of all ages and races. "In the context of inflammatory skin diseases, CCL17/TARC and CCL22/MDC production is increased epidermal keratinocytes upon stimulation with TNF-α/IFN-γ, resulting infiltration of immune cells into the lesion area." (PMID 36793948, 2023).
Insulin resistance (3 papers, 2016 to 2024). Increased resistance towards insulin, that is, diminished effectiveness of insulin in reducing blood glucose levels. "Here we report that compared with in control subjects, circulating chemokines CCL17 and CCL22 are significantly augmented in patients with morbid obesity and positively correlated with BMI and insulin resistance." (PMID 37124725, 2023).